PAX5 (paired box 5)
Diseases named in the same sentence as PAX5 in open-access papers (continued):
Sharing a sentence is not in itself a finding about the gene and the disease.
lymphoma (continued). "Immunohistochemically, these lymphoma cells were positive for CD20, PAX-5, MUM-1, BCL-6 and CD5, but negative for CD3 and CD10." (PMID 32513269, 2020). "Negativity for leukocyte common antigen (LCA) and other lymphoid markers (CD3, CD20, CD7, CD4, CD79a, CD30, CD68, PAX5, ALK1, and TdT) rules out malignant lymphoma." (PMID 29914385, 2018). "All CD19 negative lymphomas were positive for CD20, the majority was positive for PAX5, and two were positive for BCL2 and BCL6." (PMID 28484276, 2017). "The diagnosis of CD-20 negative lymphomas requires pathologists to use a comprehensive panel of markers in order to identify B-cell lineage and reflect various stages of B-cell differentiation, including staining for CD79a, CD19, and PAX5." (PMID 40612965, 2025). "Also, CMR revealed a huge heterogeneous anterior mediastinal mass, and the pathology and the immunohistochemistry of the mass biopsy revealed gray zone lymphoma with positive CD3, CD20, CD30, CD45, PAX5, and negative CD15 expression." (PMID 37259152, 2023).
acute lymphoblastic leukemia (49 papers, 2013 to 2025). Leukemia with an acute onset, characterized by the presence of lymphoblasts in the bone marrow and the peripheral blood. "WHO2022 introduced PAX5 mutations as one of the components of a new subtype, “B-acute lymphoblastic leukemia (ALL) with other defined genetic abnormalities”." (PMID 38485897, 2024). "Loss-of-function mutations in PAX5 transcription factor occur in B-progenitor acute lymphoblastic leukemia." (PMID 39408690, 2024). "It is reported that the loss of PAX5 leads to B-cell malignancies in mouse models, and the mutation of PAX5 in humans causes genetic lesions in acute lymphoblastic leukemia." (PMID 36835134, 2023). "PAX5 is indispensable for the B-cell lineage specification and maintenance and has been implicated in human B cell malignancies, including acute lymphoblastic leukemias and non-Hodgkin lymphomas." (PMID 30866419, 2019). "An alteration of PAX5 dosage induced B cell malignancies: its overexpression, secondary to the IGH-PAX5 rearrangement, is associated with B cell lymphomas and loss of heterozygosity is associated with B cell progenitor acute lymphoblastic leukemia." (PMID 30214688, 2018). "Then, it has to be considered that PAX5 is the gene with the highest frequency of somatic mutations in patients with acute lymphoblastic leukemia, resulting in lower levels of the protein, which suggests that these molecular alterations decrease the expression of this gene in some B cell lymphomas." (PMID 32604737, 2020). "Furthermore, ZNF521 is expressed in human hematopoietic cells, and translocations between ZNF521 and PAX5 are associated with pediatric acute lymphoblastic leukemia." (PMID 27506447, 2016). "The mutation of PAX5 is one of the consistent genetic alterations found in B-cell acute lymphoblastic leukemia (B-ALL)." (PMID 39408690, 2024). "Approximately 30% of the pediatric patients with B-cell precursor acute lymphoblastic leukemia (BCP-ALL) harbor a somatic heterozygous loss-of-function alteration in PAX5." (PMID 37543654, 2023). "We also compare a set of independently conducted screens from Pax5 mutant mice that converge upon a common set of mutations observed in human acute lymphoblastic leukemia (ALL)." (PMID 34484175, 2021). "For instance, increasing the expression of SMN2 may have clinical utility in patients with spinal muscle atrophy owing to SMN1 mutations, and increased expression of PAX2 or PAX8 may be of interest in patients with predisposition to acute lymphoblastic leukemia due to PAX5 mutations." (PMID 34818036, 2021). "We can therefore conclude that acute lymphoblastic leukemia (ALL), particularly its B-progenitor lineage (B-ALL), is closely linked to genetic alterations in PAX5." (PMID 40506992, 2025). "Being EBF1, together with E2A and Pax5, involved in the B-cell lineage commitment by regulating cell transcription, it has been also implicated in the development of B-cell-acute lymphoblastic leukemias (B-ALL)." (PMID 38035116, 2023). "Pax5 target genes are mostly expressed in leukemic cells and have been demonstrated as a tumor suppressor in lymphoblastic leukemia.." (PMID 35774783, 2022). "Concurrently, studies have demonstrated that PAX5 haploinsufficiency plays an essential role in lymphoblastic leukemia." (PMID 36077495, 2022). "This cell population has been observed in Pax5 haploinsufficient mice that developed a pre-B acute lymphoblastic leukemia when their immune system was overstimulated." (PMID 31381950, 2019). "PAX5 (paired box 5) plays a critical role in B cell development and leukemogenesis of acute lymphoblastic leukemia." (PMID 30142192, 2018). "Approximately one-third of individuals with pre-B acute lymphoblastic leukemia (ALL) acquire heterozygous inactivating mutations of PAX5 in malignant cells, and heterozygous germline loss-of-function PAX5 mutations cause autosomal dominant predisposition to ALL." (PMID 30216339, 2018).
acute lymphoblastic leukemia (continued). "Links between ZNF521 (the human orthologue of Zfp521) and human leukemia also exist, as a translocation that generates a chimaeric fusion protein of ZNF521 and PAX5 has been found in paediatric acute lymphoblastic leukemia." (PMID 27506447, 2016). "Two case studies, in subchondral bone in osteoarthritis and in Pax5 in acute lymphoblastic leukaemia, demonstrate that PhenomeExpress identifies core disease pathways in both mouse and human disease expression datasets derived from different technologies." (PMID 25631385, 2015). "Fusion between PAX5 and other genes in acute lymphoblastic leukemia." (PMID 37335685, 2023). "Besides, PAX5 is an important oncogene in neuroblastoma and a tumor suppressor in acute lymphoblastic leukemia." (PMID 36064939, 2022). "Mutations in the transcription factors PAX5 and IKZF1 are commonly seen in acute lymphoblastic leukaemia, suggesting that their expression may confer a selective disadvantage." (PMID 34163480, 2021). "The involvement of PAX5 in other malignant B cell tumors, such as non-Hodgkin lymphomas and acute lymphoblastic leukemias, has been described as a dysregulation provoked by chromosomal translocations due to somatic hypermutation (SHM) and class-switch recombination." (PMID 32604737, 2020). "Finally, AUTS2 is involved in translocations with PAX5 in B-cell precursor acute lymphoblastic leukemia and other cancers." (PMID 29166413, 2017). "PAX5 haploinsufficiency cooperated with BCR-ABL1 to induce acute lymphoblastic leukemia." (PMID 28316978, 2017). "In conclusion, the discovery of PAX5 fusion in acute lymphoblastic leukemia (ALL) has shed light on the genetic basis of this deadly disease." (PMID 37335685, 2023). "While PAX5 is an important tumor suppressor gene in B‐cell acute lymphoblastic leukemia (B‐ALL), it is also involved in oncogenic translocations coding for diverse PAX5 fusion proteins." (PMID 35156727, 2022). "POM121 fusion with PAX5 (a transcription factor critical in B-cell development) generates aberrant chimeric proteins in childhood acute lymphoblastic leukemia (ALL)." (PMID 34970494, 2021). "Pediatric B-cell precursor acute lymphoblastic leukemia (BCP-ALL) is associated with a high frequency of copy number alterations (CNAs) in IKZF1, EBF1, PAX5, CDKN2A/B, RB1, BTG1, ETV6, and/or the PAR1 region (henceforth: B-cell development genes)." (PMID 30874617, 2019). "PAX5 haploinsufficiency synergized with STAT5 activation to initiate acute lymphoblastic leukemia (ALL) and the probability of tumor formation was 100%." (PMID 28316978, 2017). "Acute Lymphoblastic Leukemia (ALL) is associated with mutations like IKZF1 and PAX5, along with radiation and pesticides, but its exact causes remain unclear in many cases." (PMID 41362667, 2025). "Recurrent JAK2 fusion events involving diverse partner genes—including ATF7IP, EBF1, PAX5, SSBP2, RNPC3, GOLGA5, and PCM1—have been described in a subset of acute lymphoblastic leukemia cases." (PMID 41228238, 2025). "Moreover, the B-cell lineage activating transcription factor PAX5 has been shown to directly regulate expression of tens of lncRNAs in pro-B and mature B cells as well as in acute lymphoblastic leukemia (ALL)." (PMID 35193592, 2022). "High-resolution breakpoint mapping by Optical Genome Mapping enables precise detection of clinically actionable gene rearrangements in acute lymphoblastic leukemia (ALL), including MEF2D::CSF1R and PAX5::JAK2 fusions—hallmarks of the Philadelphia-like (Ph-like) ALL subtype." (PMID 41228238, 2025). "Mutation of JAK2 is observed in several hematological disorders including ET, Polycythemia Vera, Primary Myelofibrosis and Acute Lymphoid Leukemia (ALL) as well as chromosomal translocations involving the fusion partners TEL, BCR, PCM1, PAX5, SEC 31A and SSBP2." (PMID 24086539, 2013).
acute lymphoblastic leukemia (continued). "Optical Genome Mapping (OGM) enables high-resolution detection of structural genomic alterations with established prognostic significance in acute lymphoblastic leukemia (ALL), including deletions affecting CDKN2A/B, IKZF1, and PAX5 loci." (PMID 41228238, 2025). "Genome‐wide studies demonstrated that 60% of all B‐cell precursor acute lymphoblastic leukemia (B‐ALL) cases carry genetic alterations in genes coding for regulators of B cell development, with the most commonly affected transcription factor genes being PAX5, EBF1, and IKZF1 (Ikaros)." (PMID 35156727, 2022). "The transcription factor PAX5 plays a critical role in B-cell development and differentiation and has been considered to function as a tumor suppressor in B cell precursor acute lymphoblastic leukemia (BCP-ALL)." (PMID 34513684, 2021). "A recently characterized high-risk subgroup in acute lymphoblastic leukemia (ALL) is defined by the IKZF1plus profile, which is marked by the co-occurrence of IKZF1 deletions alongside deletions in CDKN2A/B, PAX5, or the PAR1 region, in the absence of ERG gene alterations." (PMID 41228238, 2025). "Additionally, we identified a single individual with B-cell precursor acute lymphoid leukemia with two intragenic deletions involving IKZF1 and PAX5, in the absence of an ERG deletion, suggestive of the IKZF1plus phenotype." (PMID 37686670, 2023).
B-cell lymphomas (39 papers, 2012 to 2026). "The MUM-1 reaction associated with prevalent B cell marker or PAX5 immuno-expression was adopted to indicate B cell lymphoma." (PMID 36157173, 2022). "Somatic mutations in the PAX5 enhancer were also found by the authors in other types of B-cell lymphoma: DLBCL (29%), FL (23%), MCL (5%)." (PMID 34210001, 2021). "Indeed, downregulation and dysregulation of PAX5 may contribute to the higher risk of malignancy, particularly B cell lymphomas, observed among people with A-T43,44." (PMID 32366930, 2020). "Despite the absence of systemic symptoms and a vitreous sample of low cellularity, diagnostic pars plana vitrectomy confirmed large B-cell lymphoma via immunophenotyping (CD20, CD79a and PAX5)." (PMID 41948257, 2026). "All examined organs contained variable numbers of neoplastic round cells with moderate-to-marked nuclear-to-cytoplasmic immunolabeling for PAX5, consistent with B-cell lymphoma." (PMID 40359093, 2025). "PAX5::MYC fusion has been reported in high-grade B-cell lymphoma with MYC and BCL2 rearrangements, DLBCL, and transformed FL." (PMID 41374977, 2025). "T-cell lymphomas are CD3 positive, while B-cell lymphomas exhibit positive forCD20, CD79α, and paired box 5 (PAX5)." (PMID 39619931, 2024). "The CD20, CD79a, and PAX5 are commonly used to identify B cell lymphomas, while CD3 is a specific marker for T cell lymphoma." (PMID 36157173, 2022). "Contrary to its oncogenic effects in B cell lymphomas, PAX5 seems to play a role of an anti-proliferative protein in many malignancies." (PMID 34570823, 2021). "On one hand, PAX5 is involved in translocations with IGH, which lead to PAX5 upregulation in aggressive B-cell lymphomas." (PMID 34210001, 2021). "In hematopoietic malignancies, B-cell lymphomas with up-regulated AID have been shown to carry adverse mutations in genes, such as MYC, PIM1, and PAX5, as well as chromosomal abnormalities, including MYC/IGH rearrangements." (PMID 30679751, 2019). "PAX5 has a pivotal regulatory function in B-cell development and its aberrant expression is correlated with aggressive subsets of B-cell NHL." (PMID 25294155, 2014). "Normally, PAX-5 is thought to be B cell restricted, marking both B-cell lymphoma and Hodgkin's lymphoma, with expression in some AML and neural tumors and carcinomas." (PMID 23738160, 2013). "On the other hand, diagnosing B-cell lymphoma in dogs, supported by compatible cytological features and nuclear expression of PAX5, could be performed in archived cytology and CB, with a low interobserver variation." (PMID 36851461, 2023). "If CD81 gene expression could be controlled by ON or OFF Pax5-expression, Pax5-mediated CD81 regulation may be useful for the treatment of B cell lymphoma using anti-CD81 antibodies." (PMID 34824296, 2021). "In this way, we detected the induction of transcription factors genes implicated in B-cell differentiation and activation, PAX5 and IRF8 as well as of MYBL2, a transcription factor participating in cell cycle progression and recently described as a direct Notch1 target in B cell lymphomas." (PMID 31676012, 2019). "Immunohistochemistry revealed CD20(+), PAX5(+), BCL2(+), and monoclonal IgH rearrangement, consistent with low-grade B-cell NHL, most likely extranodal marginal zone lymphoma (ENMZL), non-gastric/non-cutaneous type." (PMID 41800064, 2026). "It was found that B-cell lymphomas were highly labeled with CD20, CD45, PAX-5, whereas T-cell lymphomas were heavily labeled with CD3, CD5." (PMID 41960458, 2026). "GPM confirmed the presence of both IGH::BCL2 and PAX5::MYC, along with 11q aberrations and other complex genomic abnormalities, supporting a diagnosis of DLBCL/high-grade B-cell lymphoma with MYC and BCL2 rearrangements." (PMID 41374977, 2025). "Patient #16 was diagnosed with B-cell lymphoma—follicular (FL), consistent with grade 2–3A based on the proliferation index (CD20+, CD10+, BCL6+, PAX5+, CD23–, Ki-67 ~50%)." (PMID 40572665, 2025).
B-cell lymphomas (continued). "Most B cell lymphomas are positive for one or more B cell markers including CD19, CD20, CD79a, or PAX5." (PMID 39055348, 2024). "T-cell lymphomas are CD3 positive, while B-cell lymphomas are positive for CD20, CD79α, and paired box 5 (PAX5)." (PMID 39619931, 2024). "We also found B-cell lymphoma related key genes such as HOX and PAX5 deregulated at the DNA methylation level in future NHL compared to controls." (PMID 35864305, 2022). "Based on the immunophenotyping, 14 dogs were B-cell lymphomas (Pax5+, CD3-) and six dogs were T-cell lymphomas (Pax5-, CD3+)." (PMID 35765478, 2022). "All of the cats were diagnosed with large‐cell lymphoma, and five of them were further classified as having B‐cell lymphoma based on immunocytochemistry (positive for PAX‐5 and negative for CD3)." (PMID 40119555, 2025). "Additionally, B-cell lymphomas stain positive on polyclonal PAX8 preparation, while also manifesting cross-reaction with PAX5." (PMID 36428491, 2022). "Occassionally, the tumor cells of EATL are immunoblast-like and mimic the cells of DLBCL, but they do not express B cell markers such as CD20 and Pax-5 which are always expressed in DLBCL (like other B cell lymphomas)." (PMID 23217032, 2012). "In some cases of B-cell lymphoma, CD79α may display a negative result, while PAX5 and CD20 may reveal a positive result." (PMID 39619931, 2024). "Therefore, EBF1, PAX5, and MYC lesions may drive B-cell malignancy and induce B-cell lymphomas." (PMID 38318177, 2024). "Although these B-cell lymphomas did not express CD20, they stained positively for alternative markers such as MUM1, CD79a, and PAX5." (PMID 40287766, 2025). "An immunohistochemical (IHC) stain panel showed positive for CD18, thus supporting the diagnosis of round cell tumor, but negative for T- and B-cell lymphomas, CD3, CD20, and PAX-5." (PMID 36875999, 2023). "In this species, PAX5 immunostaining in RSC was not related to the CB, with only a single B-cell lymphoma (out of 3) clearly diagnosed by RSC." (PMID 36851461, 2023). "Because immunohistochemical staining against LCA, PAX-5, and SOX-10 was negative, we excluded the possibility of B-cell lymphoma and uveal melanoma." (PMID 34355005, 2021). "In contrast to other B-cell lymphomas, PBL cells usually show no expression of B-cell markers [CD20 and paired box homeotic gene 5 (PAX5)], but instead demonstrate a plasma cell phenotype with expression of CD138, CD38, MUM1, and cytoplasmic immunoglobulins." (PMID 28379189, 2017).